CA8 (carbonic anhydrase 8 (inactive))
Description:
Does not have a carbonic anhydrase catalytic activity.
Synonyms: CARP; CA-VIII; CALS; CA-RP; CAMRQ3; SCAR34
Tractability: Small molecule: it belongs to a druggable protein family. PROTAC: ubiquitination databases record sites on it.
Gene: Protein-coding gene on chromosome 8 (60,185,412 to 60,281,573, reverse strand). Ensembl gene ENSG00000178538.
Gene Ontology:
Molecular function: protein binding; carbonate dehydratase activity; zinc ion binding
Cellular component: cytoplasm
Genetic constraint (gnomAD): Loss-of-function variants: 11 observed, 26.09 expected, observed/expected ratio (o/e) 0.42, 90% interval 0.26 to 0.7. The upper end of that interval is the gene's LOEUF score, 0.7, which puts it in group 2 of 6, group 1 being the genes least tolerant of losing a copy. Missense variants: 220 observed, 293.03 expected, observed/expected ratio (o/e) 0.75, 90% interval 0.67 to 0.84. Synonymous variants: 93 observed, 110.81 expected, observed/expected ratio (o/e) 0.84, 90% interval 0.71 to 1.
Gene-disease validity (ClinGen):
ClinGen rates the evidence that CA8 causes each of these diseases.
cerebellar ataxia (autosomal recessive): Moderate.
Homologues: Orthologues: chimpanzee CA8 (100% identical), dog CA8 (99% identical), pig CA8 (99% identical), mouse Car8 (99% identical), rat Car8 (99% identical), guinea pig CA8 (87% identical), macaque CA8 (87% identical), tropical clawed frog ca8 (79% identical), zebrafish ca8 (79% identical), Drosophila melanogaster CAH6 (31% identical), Drosophila melanogaster CAH9 (29% identical), Drosophila melanogaster CAH16 (28% identical), and 11 more. Paralogues in human: CA7 (37% identical), CA2 (36% identical), CA13 (36% identical), CA3 (33% identical), CA1 (33% identical), CA5B (33% identical), CA5A (32% identical), CA12 (31% identical), CA9 (30% identical), CA6 (29% identical), CA14 (29% identical), CA11 (28% identical), and 2 more.
Diseases named in the same sentence as CA8 in open-access papers:
CA8 is named in the same sentence as 25 diseases in open-access papers, as found by Europe PMC text mining. Sharing a sentence is not in itself a finding about the gene and the disease. The quoted sentences say what the papers report.
Ataxia (14 papers, 2009 to 2026). Ataxia refers to impaired coordination of voluntary muscle movement. "Intriguingly, disabling mutations in CA8 cause spinocerebellar ataxia in humans, which is a neuromuscular disorder involving disrupted Ca2+ signaling that in some instances results in quadrupedal locomotion in patients." (PMID 40783389, 2025). "Nevertheless, Ca8 is highly expressed in Purkinje cells in which it regulates dendritic growth and mutated Ca8 leads to cerebellar ataxia." (PMID 33912010, 2021). "Mutations in CA8 can cause ataxia and mild mental retardation VPS26 plays a role in sensitisation to pain diabetes susceptibility and is involved in trafficking and sorting of transmembrane proteins." (PMID 31067744, 2019). "Recessive CA8-null mutants are associated with spinocerebellar ataxia and neurodegenerative disorders." (PMID 31199789, 2019). "Patients with mutations in CA8 show phenotype in cerebellar ataxia, mental retardation, and disequilibrium syndrome, while CA8−/− mice exhibit motor dysfunction and altered calcium dynamics in cerebellar granule cells." (PMID 27809276, 2016). "In addition, mutations in CA8 gene have been implicated in a closely related syndrome that is characterized by ataxia and mild mental retardation with predisposition to quadrupedal gait." (PMID 22973972, 2012). "Indeed the role of CARP VIII is evident from the recently published reports showing ataxia and gait disorders in both mice and humans due to mutations in the CA8 gene." (PMID 20356370, 2010). "We find that splicing aberrations disrupt the expression of many key cerebellar PC genes, many of which (e.g., Itpr1, Grid2, Ca8, Bean1, etc.)can individually compromise cerebellar function and lead to ataxia." (PMID 34910524, 2021). "Behavioural studies in the wdl mouse (19-bp deletion in CA8-gene on exon 8), and in CA-VIII knock down zebrafish models demonstrated phenotypes similar to human ataxia highlighting significant importance to motor function." (PMID 32316137, 2020). "The condition has been classified into cerebellar ataxia, mental retardation and disequilibrium syndrome types 1 (CAMRQ1), 2 (CAMRQ2) and 3 (CAMRQ3) and attributed to mutations in VLDLR, CA8 and WDR81 genes, respectively." (PMID 22973972, 2012). "Another recent study described mild mental retardation, quadrupedal gait and ataxia in members of an Iraqi family who each possessed a defect in the CA8 gene." (PMID 20356370, 2010). "Thus, in the double-mutant cerebellum, widespread abnormalities occur, involving a notable cohort of critical neuroregulatory genes including Itpr1, Grid2, and Ca8, whose perturbation in humans underpin ataxia syndromes." (PMID 34910524, 2021). "Given CA8 deficiency is associated with severe spinal cerebellar ataxia and that we have reported CA8 is critical to nociception, inflammatory and neuropathic pain, neuronal DRG wildtype CA8 (transcript CA8-201) deficiency associated with G/G genotype should display a deleterious phenotype." (PMID 31199789, 2019). "This mutation probably represents a null mutation similar to the 19 bp deletion in the Ca8 gene of the waddles mouse (a spontaneous animal model with ataxia), in which the lack of detectable Ca8 protein in the cerebellum results in abnormalities in cerebellar synaptic morphology and function." (PMID 26716990, 2015). "The waddles (wdl) mouse, a spontaneous animal model with ataxia, was previously shown to harbor a 19-bp deletion in Ca8 that leads to an almost complete lack of detectable Ca8 protein, resulting in abnormalities in cerebellar synaptic transmission." (PMID 19461874, 2009).
Intellectual disability (5 papers, 2009 to 2020). "Mutations in CA8 cause a recessive form of congenital ataxia associated with mild intellectual disability." (PMID 22986007, 2012). "There was also overlap for genes involved in intellectual disabilities, including AFF2, AIFM1, CA8, EEF1A2, MLC1, and XYLT1, but statistically the overlap is not significant." (PMID 32393163, 2020).
osteosarcoma (3 papers, 2018 to 2023). A usually aggressive malignant bone-forming mesenchymal neoplasm, predominantly affecting adolescents and young adults. "Recent study showed an increased expression of CA8 gene in more aggressive types of human osteosarcoma (HOS) cells and the CA8 expression correlated with the disease stages, showing intense expression in the late stages of the disease." (PMID 29792187, 2018). "In studies of lung cancer and osteosarcoma, CA8 is considered an oncogene." (PMID 35625769, 2022).
Colon Cancer (2 papers, 2022 to 2024). "CA8 showed superior chemical and physical qualities and excellent safety, as well as an anti-colon cancer activity in vitro and in vivo by activating the JNK pathway and inhibiting the AKT pathway." (PMID 39600365, 2024). "Therefore, CA8 is a potential promising novel anti-colon cancer drug, which deserves further investigation." (PMID 39600365, 2024). "Moreover, CA8 showed a strong colon cancer toxicity, and our speculation was that CA8 has the best oral bioavailability due to its high solubility." (PMID 39600365, 2024).
CAMRQ syndrome (1 paper, 2025). "CAMRQ syndrome can arise from pathogenic variants in several genes including the very low‐density lipoprotein receptor (VLDLR) (CAMRQ1; MIM: 224050), WD repeat domain 81 (WDR81) (CAMRQ2; MIM: 610185), carbonic anhydrase 8 (CA8) (CAMRQ3; MIM: 613227) and ATP8A2 designated as CAMRQ4 (MIM: 615268)." (PMID 39931767, 2025).
Cerebellar atrophy (1 paper, 2009). Cerebellar atrophy is defined as a cerebellum with initially normal structures, in a posterior fossa with normal size, which displays enlarged fissures (interfolial spaces) in comparison to the foliae secondary to loss of tissue. "Mice with mutations in either Ip3r1 or Ca8 do not display cerebellar atrophy, but rather both show neurophysiological defects." (PMID 19461874, 2009).
COVID-19 (1 paper, 2025). A disease caused by infection with severe acute respiratory syndrome coronavirus 2. "The risk locus rs2875968 spans three genes (RAB2A, LINC01301, and CA8), none of which have strong prior evidence implicating them in COVID-19 physiopathology." (PMID 40208878, 2025).
leukemia (1 paper, 2021). A malignant (clonal) hematologic disorder, involving hematopoietic stem cells and characterized by the presence of primitive or atypical myeloid or lymphoid cells in the bone marrow and the blood. "Among the other genes with strong correlations between DNA methylation and gene expression, aberrant DNA methylation and downregulation of FKBP9, CA8, MSC, TRPC6, ZNF492, ZNF229, and ZNF471 genes in leukemia patients are reported here for the first time." (PMID 34575904, 2021).
vitiligo (1 paper, 2025). Generalized well circumscribed patches of leukoderma that are generally distributed over symmetric body locations and is due to autoimmune destruction of melanocytes. "Finally, we obtained ten matched genes (GP1BA, ANKS4B, CCDC87, CA8, HLA‐DOB, RHEBL1, NLRP7, GZMH, HERPUD1, and MAP2K1) as a vitiligo‐gene signature (VGS)." (PMID 40974370, 2025).
tumor (7 papers, 2015 to 2025). "Thus, we speculate that the low expression or loss of activity of oncogenes such as CA8 is one of the reasons for the high expression of tumor suppressor genes such as K17, GATA4 and p16lnk4a." (PMID 33324659, 2020). "Taken together, CA8 inhibited tumor growth more effectively than the other tested drugs, which was consistent with the results of in vitro pharmacodynamics." (PMID 39600365, 2024). "The immunohistochemical results revealed that CA8 significantly reduced the expression of Ki67 in tumor tissues." (PMID 39600365, 2024). "All cancer cells used in this study were highly sensitive to CA8, which indirectly proved that CA8 has broad-spectrum anti-tumor properties." (PMID 39600365, 2024). "In our study, IκBα was significantly upregulated following CA8 treatment, suggesting that the apoptotic effects of CA8 on tumor cells may also involve the NF-κB signaling pathway." (PMID 39600365, 2024). "Through Western blot analysis, we found that CA8 may promote tumor cell apoptosis and inhibit proliferation by regulating the AKT, NF-κB, and mitochondrial apoptosis pathways." (PMID 39600365, 2024). "CA8 also inhibited the proliferation and angiogenesis of tumor cells more than CU and tegafur." (PMID 39600365, 2024). "Finally, CA8 may exert anti-tumor effects through the activation of JNK pathway and inhibition of AKT pathway." (PMID 39600365, 2024). "Moreover, the results of q-RT PCR showed that CTSV, RGS4, SYT13 and NPTX1 were highly expressed in tumor tissues compared with adjacent tumor tissues, while SLC25A15, ENTPD2 and CA8 were low expressed." (PMID 36684237, 2022).
infection (6 papers, 2017 to 2024). The state of being infected such as from the introduction of a foreign agent such as serum, vaccine, antigenic substance or organism. "SH-SY5Y cells after RA differentiation expressed high levels of CA8*WT peptide (using V5-tag) on western blots after infection with vHCA8*WT, as compared to CA8*MT (V5-tag) after vHCA8*MT infection, or vehicle control at Baseline." (PMID 39086927, 2024).
CA8 also shares sentences with these, for which no sentence is quoted: cerebellar ataxia (8 papers); cancer (2); renal cell carcinoma (2); colorectal cancer (1); diabetes (1); Dystonia (1); Joubert syndrome (1); lung carcinoma (1); neuroblastoma (1); Niemann-Pick disease type C (1); osteoporosis (1); pancreatic cancer (1); progressive ataxias (1); sarcoma (1).